SIRT1 (sirtuin 1)
Diseases named in the same sentence as SIRT1 in open-access papers (continued):
Sharing a sentence is not in itself a finding about the gene and the disease.
cancer (continued). "With statistical analysis (Mann-Whiney 2-tailed test), it was found that SIRT1 protein expression was significantly decreased in carcinomas than in adjacent noncancerous mucosae (P<0.001, 1.81-fold)." (PMID 23805287, 2013). "Sirtuin 1 acts in various cell processes, deacetylating both chromatin and non-histone proteins, and its role in cancer and aging has long been studied and debated." (PMID 21307403, 2011). "In conclusion, the present study demonstrates that 15d-PGJ2 has a high therapeutic potential to kill drug-resistant tumor cells and, the newly described inhibitory effects of this cyclo-oxygenase product on SIRT1 and HDAC will provide new opportunities for cancer therapeutics." (PMID 21957481, 2011). "Since expression of both CK2 and SIRT1 is upregulated with tumorigenesis and downregulated with senescence, the CK2-SIRT1 link sheds new light on how CK2 may regulate cancer development and aging." (PMID 19680552, 2009). "One possible scenario that ties this role of SIRT1 to a cascade of epigenetic events observed in cancer comes from our recent observation that HIC1, a gene that is frequently epigenetically silenced early in tumorigenesis, can be localized to the SIRT1 promoter." (PMID 16596166, 2006). "However, the SIRT1-mediated deacetylation of FOXO3 at multiple lysine residues (K242, K259, K271, K290, and K569) alters its transcriptional output and nuclear localization in cancer cells." (PMID 41008982, 2025). "Therapeutically, the inhibition of SIRT1 to restore p65 K310 acetylation and reactivate the SASP may represent a promising strategy to trigger tumor-suppressive senescence and enhance the immune-mediated clearance of cancer cells." (PMID 41008982, 2025). "However, studies analyzing the efficacy of CANA in treating CCA or the effect of SIRT1 activation by CANA on cancer cells are lacking." (PMID 39940750, 2025). "Additionally, SIRT1 facilitates E2 protein degradation in the absence of TopBP1, driving viral genome integration and cancer progression." (PMID 41471349, 2025). "Hence, while arzanol inhibits SIRT1 in hippocampal tissue with resultant effects on FOXO1 signaling, the consequences of this same molecular interaction in cancer cells may differ." (PMID 41304625, 2025). "Furthermore, integrating SIRT1-targeted therapies with immuno-metabolic strategies and deepening our understanding of the NAD+–SIRT1–redox axis will pave the way for precision medicine approaches in redox-dependent cancers." (PMID 41008982, 2025). "In cancer cells, the excessive activation of PARPs significantly increases the catabolism of NAD+, resulting in a concomitant rise in NAM levels and a reduction in NAD+ concentrations, which may markedly reduce the deacetylase activity of SIRT1." (PMID 40427612, 2025). "Almost 80% of cancer tissues expressed Sirt1 but normal tissues did not." (PMID 38427808, 2024). "Additionally, recent studies have demonstrated the potential effect of activating the SIRT1–adenosine monophosphate-activated protein kinase (AMPK)/FOXO3 pathway in terms of reversing the chemoresistance and proliferation of cancer stem cells in human gastric cancer tissues." (PMID 39683482, 2024). "Silent information regulator 2 homolog 1 (SIRT1) is an epigenetic factor belonging to the sirtuin (SIRT) family known to regulate aspects of chromatin biology, genome stability, and metabolism, both in homeostasis processes and in different diseases, including cancer." (PMID 37833921, 2023). "It is not clear at all how estradiol can affect SIRT1 expression in different cancer cells." (PMID 37762053, 2023).
cancer (continued). "In this aspect, SIRT1, augmenting HSP90 expression, might play an important function in assuring proper levels of HSP90 to form key chaperomes/epichaperomes in cancer cells exposed to multiple external and internal stressors, resulting from changing microenvironmental conditions or therapy." (PMID 37816710, 2023). "Unlike in cancer cells, the reduction in SIRT1 activity in primary fibroblasts (by the direct inhibition of SIRT1 or as a consequence of chronological aging) was associated with some increase in the prevalence of R-loops, but not with a genome-wide activation of dormant origins." (PMID 37998365, 2023). "The SIRT1/FOXO pathway is activated by cellular oxidative stress and may allow the development of new strategies for the prevention and treatment of skin cellular senescence, inflammation, and cancer." (PMID 36835162, 2023). "However, not in all cancer cells, even those commonly considered to be highly dependent on sex steroids, does estradiol have an effect on changes in SIRT1 expression." (PMID 37762053, 2023). "Given the importance of SIRT1 and c-Myc in regulation of stem cell self-renewal, pluripotency, and differentiation, it is not surprising that the SIRT1-c-Myc axis revealed in cancer research is also functionally important in stem cell biology and animal embryonic development." (PMID 37554307, 2023). "Therefore, anti-HO1 therapy that restores NK immunity may be widely useful for treating cancer, especially in AML patients with high HO1 and Sirt1 expression." (PMID 36058936, 2022). "Notably, unlike normal cells, in cancer cells the anti-senescence effects of SIRT1 is not considered beneficial, as SIRT1 overexpression is observed in several solid cancers and is associated with a poor overall survival." (PMID 36138054, 2022). "Therefore, SIRT7 and SIRT1/SIRT6 play opposite roles in the metabolism, inflammation, and cancer." (PMID 36012298, 2022). "Given that this is the cell microenvironment in which AMPK inhibition may limit cancer cell population growth, what are the alternative means of simultaneously suppressing mTORC1 and mTORC2, if not via SIRT1 inhibition?" (PMID 35078427, 2022). "The function of SIRT1 in cancer development is complex and still not completely understood." (PMID 34866322, 2022). "Notably, it has been revealed that SIRT1 deacetylates and upregulates the expression of matrix metalloproteinase-2 (MMP2), a zinc-dependent endopeptidase that degrades the extracellular matrix to promote the invasion of cancer cells." (PMID 36291902, 2022). "Overexpressed LINC00842 may directly interact with acetylated PGC-1α, an important transcription co-regulator in the metabolic pathways, and blocks SIRT1 to deacetylate acetylated PGC-1α, resulting in metabolic remodeling, i.e., enhancing anabolism but reducing catabolism in cancer cells." (PMID 34158490, 2021). "Knock-down and overexpression studies in cancer cell lines suggest that Usp22 may promote cancer through the positive regulation of well-known oncogenes including BMI1, c-MYC, SIRT1, cyclin B1, and KDM1A, mainly through the regulation of cell cycle progression." (PMID 34503086, 2021). "Considering that NNMT upregulation in the liver does not decrease NAD+ level, in contrast to adipose tissue, concomitant stabilization of SIRT1 by NNMT and the ability of liver to synthesize NAD+ de novo from Trp may allow for SIRT1 overactivation in this type of cancer." (PMID 34073600, 2021). "Moreover, CART, SIRT1, and PER2 negatively correlated with the infiltration of M2 cells show good prognosis of cancer patients, while SERPINE1 and NFIL3 positively correlated with the infiltration of M2 cells show poor prognosis of cancer patients." (PMID 31927791, 2020).
cancer (continued). "The present data reveal that CBP- and SIRT1-driven reversible acetylation of HINT1 at both K21 and K30 affects the capacity of HINT1 to bind to β-catenin or MITF, which, in turn, can influence its tumor-suppressive activity in cancer cell lines and in an in vivo xenograft mouse model." (PMID 32636443, 2020). "Finally, we found that JQ1 treatment induced ferroptosis by suppressing BRD4 expression via the inhibition of the histone methylase G9a or activation of the histone deacetylase SIRT1 as there are enhanced H3K4me3 and H3K27ac levels at upstream of BRD4 in cancer." (PMID 30988278, 2019). "Finally, SIRT1 overexpression does not appear to be a cancer-initiating event but rather a cancer-induced adaptive mechanism that promotes survival and proliferation." (PMID 31608282, 2019). "Based on the existing literatures, we find (a) coptisine exerted potential to be an anti‐cancer, anti‐inflammatory, CAD ameliorating or anti‐bacterial drug through regulating the signalling transduction of pathways such as NF‐κB, MAPK, PI3K/Akt, NLRP3 inflammasome, RANKL/RANK and Beclin 1/Sirt1." (PMID 31622015, 2019). "Importantly, SOX17 transcriptionally down-regulated DNA repair and damage response-related genes including BRCA1, BRCA2, RAD51, KU80 DNAPK, p21, SIRT1, NFAT5 and REV3L in KYSE510 radio-resistant cells to achieve the sensitization effect to anti-cancer treatment." (PMID 30777052, 2019). "Interestingly, the functional significance of NAMPT on sirtuins is likely cancer cell type specific, since changes in SIRT1 expression with NAMPT inhibition have not been observed in all NAMPT inhibitor-sensitive cells." (PMID 32010616, 2019). "The specific mechanism used by benzimidazole to inhibit SIRT1 and 2 has not been clearly defined, but these novel derivatives provide a new trajectory for developing new therapeutic drug agents to fight various types of cancers." (PMID 31683808, 2019). "Finally, sirtuin 1 (SIRT1), which deacylates histones and non-histone proteins, was increased in si-hVDAC1-TTs derived from the three cancer types." (PMID 30544833, 2018). "However, osteoblastogenesis might also be altered by the SIRT1‐FoxO axis and where FoxO activation of BMP2 in anti‐cancer treatments might suggest an overlapping role in RSV‐SIRT1 induced BMP2 activation in osteoblasts also." (PMID 30125963, 2018). "Therefore, SIRT1, as an epigenetic factor, may be activated by ROS production under ADT to facilitate cancer cell survival through activation of Akt." (PMID 29416748, 2018). "The functions of histone deacetylases (HDACs), a class of total eighteen proteins (HDAC1–11 and SIRT1–7 in mammals) that deacetylate histones and non-histone proteins, in cancers are largely unknown." (PMID 29126425, 2017). "Accordingly, this context-dependent role of SIRT1 represents a target for selective killing of cancer versus non-cancer cells, and a recent drug screening approach has led to the identification of a potent SIRT1/2 inhibitory substance with potential use in cancer therapy." (PMID 27916001, 2016). "In contrast, SIRT1 within cancer cells has a negative effect on cell proliferation." (PMID 26992208, 2016).
cancer (continued). "In a previous study, we found that SIRT1-dependent deacetylation levels in histones within the MCAM promoter were lower in HCC cells than in other cancer cell types, suggesting that histone deacetylation may not be a major function of SIRT1 in HCC cells." (PMID 26824501, 2016). "We speculate that while cancer cells often feature an increased antioxidant capacity, high level of SOD1 acetylation represents an intrinsic silencing of SOD1, and is also an indicator of low activity of SIRT1." (PMID 26008972, 2015). "Moreover, pharmacological inhibition of SIRT1/2 interferes with the Wnt pathway by decreasing the expression of Dishevelled proteins, frizzled 7 receptor (FZD7) and beta-catenin in various cancer cells, which ultimately leads to inhibition of cell growth and cell migration." (PMID 25915617, 2015). "Interestingly, SIRT1 has been found to localize at the promoters of these methylated-silenced tumor suppressor genes in some cancer cells, but not to promoters of the same tumor suppressor genes were they are normally in an active state." (PMID 26459286, 2015). "Interestingly, SIRT1 interacts with HIC1, a tumor suppressor and transcriptional repressor that is epigenetically inactivated but not mutated in human cancers." (PMID 25486244, 2014). "We report here a new SIRT1 inhibitor JQ-101, a compound possessing a polyprenylated acylphloroglucinol (PPAP) core, which exhibits selective inhibition of tumor cell line growth and survival though induction of apoptosis and cellular senescence, and significantly suppresses cancer cell invasion." (PMID 25189993, 2014). "While it is recognized that tumor promoters and suppressors are significant in tumor development, no analyses of Sirt1 overexpression in a large number of surgically resected human cancer tissues have been reported, nor has the clinical significance of Sirt1 been properly ascertained." (PMID 24959282, 2014). "Knock-down of SIRT1 enhanced apoptosis only in the cancer cells, but not in normal cells." (PMID 24019980, 2013). "Of note, no significant changes in Sirt1 expression wasobserved in cells treated with any of the approaches tested, further confirmingthe difference in response to these treatment between normal and cancer cells." (PMID 20195491, 2009). "On the one hand, SIRT1 is upregulated in tumors and cancer cells lacking the tumor suppressor gene, HIC1, can inhibit apoptosis and down-regulates the expression of tumor suppressor genes, leading many to conclude that SIRT1 will prove to be an oncogene in vivo." (PMID 18414679, 2008). "To examine this, we compared by RT-PCR and by quantitative real-time RT-PCR the re-expression achieved by SIRT1 knockdown of two genes with the basal expression of these same genes in an another cancer cell line in which the promoter DNA is not hypermethylated." (PMID 16596166, 2006). "However, a comprehensive exploration of SIRT1’s involvement in pan-cancer remains lacking." (PMID 39845948, 2024). "Notably, in HUVEC cells, S1P upregulates Sirtuin 1 that, in turn, stimulates angiogenesis, although the exact mechanism, and whether or not it also occurs in cancer cells, is unknown." (PMID 36982369, 2023).
cancer (continued). "After showing Sirt1 dependent effects in non-cancerous mouse cells we wanted to investigate whether our new inhibitors have an impact on proliferation, migration and colony forming properties of human cancer cells." (PMID 32426286, 2020). "Thus, the maintenance of adequate intracellular NAD+ levels and properly SIRT1 and PARP-1 activity is important in preventing DNA damage, genomic instability, and chronic inflammation that seems to be the major contributor to the cancer incidence increase in elderly." (PMID 31779194, 2019). "However, the role of SIRT1 in cancer has not been clearly defined." (PMID 26999517, 2016). "Importantly, SIRT1 inhibition had less of an effect on proliferation and apoptosis of normal CD34+ cells, suggesting that SIRT1 might be a new target for eliminating CML cancer stem cells." (PMID 25749979, 2015). "However, its role in the resistance to the stresses suggested that SIRT1 could be involved in the progression of cancers by regulating histone and non-histone proteins." (PMID 24019980, 2013). "Both SIRT1 and PARP1 play an intimate role in the regulation of genomic stability, and continued work is necessary for the understanding of the specific contexts in which modulators of SIRT1 and PARP1 activity may be appropriate as therapeutics for cancer and metabolic disorders." (PMID 24360018, 2013). "So far, no studies have evaluated the effects of CANA on SIRT1 and NAD+ salvage pathways in cancer cells." (PMID 39940750, 2025). "Sirt1 suppression itself does not lead to cancer cell death, requiring Sirt6- and MDM2-mediated downregulation to induce an anti-cancer effect." (PMID 38254877, 2024). "miRNA-128–2 (associated with apoptosis and cholesterol homeostasis) in HepG2, MCF7, and HEK293T cancer cell lines increases SREBP2 expression and decreases SREBP1 expression independent of SIRT1 status." (PMID 36969840, 2023). "Cancer incidence was similar between genotypes at the time of natural death, and non-significantly lower in SIRT6 and SIRT1 + 6-tg mice at 25 months of age." (PMID 34050173, 2021). "In B16F10 cancer cells, however, the MMP3 level was found to be consistent regardless of SIRT1 expression." (PMID 26992208, 2016). "In human cancers, the deletion of DBC1 was not a common phenomenon and the balance between SIRT1 and DBC1 was disrupted in human cancers." (PMID 25823848, 2015). "Remarkably, in contrast to H2AFZ, although levels of H2A.Z were increased nearby the SIRT1 TSS, the canonical histone was not depleted, depicting a common feature of poised or poorly transcribed genes in cancer cells." (PMID 24127549, 2013). "Immunohistochemical assay was performed to investigate the protein expression of SIRT1 and DBC1 in 120 carcinomas (LSCCs and HSCCs) and 54 adjacent noncancerous mucosae." (PMID 23805287, 2013). "Quantitative RT-PCR was performed to confirm SIRT1 and DBC1 mRNA expression in 54 pairs of carcinomas (LSCCs and HSCCs) and adjacent noncancerous mucosae." (PMID 23805287, 2013). "Although, an earlier study reported that CHFR could promote SIRT1 degradation under oxidant stress, whether CHFR took part in regulating in maintaining the redox homeostasis in cancer was not examined." (PMID 37024798, 2023). "Additionally, we observed a negative correlation between MACC1 and two cancer and clock modulators, namely HRAS and SIRT1, known to affect the period of oscillation." (PMID 35884519, 2022). "However, no studies have evaluated the effects of CANA on SIRT1 and NAD+ pathways in cancer cells." (PMID 39940750, 2025).
cancer (continued). "−Aqueous extract from leaves and seeds had anti-proliferative and pro-apoptotic effects only on cancer cells (not on peripheral blood mononuclear cells—PBMCs).−Pro-apoptotic effect seen with aqueous extract is related with decreased BCL2 levels and sirtuin-1 (SIRT1) protein expression." (PMID 35956938, 2022).